HDAC2 (histone deacetylase 2)
Diseases named in the same sentence as HDAC2 in open-access papers (continued):
Sharing a sentence is not in itself a finding about the gene and the disease.
tumor (continued). "All these findings demonstrate that PJA2 interacts with HDAC2 to promote the polyubiquitination and degradation of HDAC2, eliminating the transcriptional inhibition of the IFIT family and PJA2 caused by HDAC2, forming a positive feedback loop and inhibiting tumor proliferation." (PMID 39928532, 2025). "In addition, IHC staining of transplanted tumor tissue sections revealed that both the inhibition of autophagy and suppression of proliferation caused by HDAC2 knockdown were reversed by ectopic expression of LAPTM4B." (PMID 39147759, 2024). "Transmission electron microscopy (TEM) examination revealed that the formation of double-membrane capsules, characteristic of autophagy, was reduced in HDAC2-deficient HCC tumor cells, and the number of autophagosomes significantly increased following HDAC2 overexpression." (PMID 39147759, 2024). "High levels of HDAC2 were associated with tumor-node-metastasis stages of OSCC patients." (PMID 36968022, 2023). "We next analyzed the clinical outcome of tumor-associated immune B-cell subsets regulated by HDAC2." (PMID 37046620, 2023). "However, other studies in humans associated the expression of HDAC2 with some prognostic factors such as histological grade, presence of metastasis in lymph nodes, and clinical stage of the tumor." (PMID 38028583, 2023). "Histone deacetylase 2 levels are also associated with tumor aggressiveness in gastric cancer." (PMID 37834214, 2023). "Moreover, the protein level of HDAC2 is associated with the histological differentiation of cancer cells and the tumor-node-metastasis stage, which describes the extent and spread of the tumor." (PMID 38067304, 2023). "HDAC2 was highly expressed in tumor tissues, and its level was associated with patients’ survival." (PMID 37171044, 2023). "HDAC-2 was significantly associated with tumor aggressiveness and lymph node metastasis." (PMID 34441281, 2021). "Importantly, HDAC-2 expression was associated with tumor histological type, being higher in the epithelioid cell than in spindle cell morphology." (PMID 34638249, 2021). "However, HDACs also display tumor suppressive effects in some cancers, e.g. an HDAC2 truncating mutation was observed in human epithelial cancers." (PMID 29126425, 2017). "HDAC-1 and HDAC-2 were significantly associated with higher tumour grades." (PMID 24624923, 2014). "For instance, low expression of HDAC1/HDAC2 in the epidermis might cause a predisposition towards neoplasia." (PMID 24240174, 2013). "High HDAC2 expression was significantly associated with poor tumor differentiation (p = 0.039)." (PMID 19912635, 2009). "However, the presence of positive nuclear HDAC-2 expression and the pattern of HDAC-2 nuclear staining showing isolated clusters of tumor cells were observed to be associated with favorable patients’ prognosis (log rank test, p = 0.04 and p = 0.001, respectively)." (PMID 34638249, 2021). "We found that HDAC2 overexpression promoted tumor growth in vivo, as evidenced by increased tumor volume and weight when compared to the control group." (PMID 41408324, 2025). "Epigenetic downregulation of NLRP3/GSDMD by histone deacetylase 2 (HDAC2) can reduce anti-tumor therapeutic efficacy." (PMID 41291696, 2025). "Investigations using TCGA database revealed a marked upregulation of HDAC2 in BCa specimens relative to the adjacent non-tumor tissues." (PMID 41408324, 2025). "The observation that HDAC2, which is known to play an important role in tumor development and progression, is overexpressed in ES makes it an attractive therapeutic target." (PMID 41463266, 2025). "Patchoulol targets histone deacetylase 2 (HDAC2) and c-Myc oncogenes and activates NF-kB transcription factors to promote apoptosis, further suppressing tumor growth." (PMID 40219102, 2025).
tumor (continued). "Consistently, the IHC‐score verified that the expression at protein levels of HDAC2 was higher in tumor tissues, and Kaplan‐Meier analysis disclosed a poor prognosis correlated with HDAC2 expression." (PMID 39928532, 2025). "In vitro functional assays, including CCK-8, colony formation, transwell and apoptotic assays, as well as in vivo assays in a nude mouse subcutaneous tumor model, were performed to assess the oncogenic and drug-resistant effects of HDAC2." (PMID 41408324, 2025). "In conclusion, our study sheds light on the intricate roles of HDAC1 and HDAC2 as tumor suppressors in ALCL development and highlights the therapeutic potential of HDAC inhibitors, such as Entinostat, in this context." (PMID 40175628, 2025). "In this context, PJA2 is recognized as a tumor suppressor that can inhibit tumor proliferation and promote apoptosis by restraining HDAC2‐related transcription of the IFIT family." (PMID 39928532, 2025). "To further validate the role of HDAC2 in vivo, we established a subcutaneous xenograft tumor model using the BCa cell line UM-UC-3 in Balb/c nude mice." (PMID 41408324, 2025). "Xenograft tumor models showed that the group with HDAC2 knockdown or treatment with Romidepsin suppressed tumor weight and volume compared with tumors with PJA2 knockdown alone." (PMID 39928532, 2025). "In vitro assays showed that the knockdown of HDAC2 and the treatment with Romidepsin rescued the anti‐tumor effect of PJA2 in SW480 and RKO cells." (PMID 39928532, 2025). "Hypoxia present in rapidly growing tumor tissue induce histone deacetylase 2 (HDAC2)-dependent deacetylation of membrane PD-L1, and promotes its nuclear translocation." (PMID 38384472, 2024). "Next, we evaluated the tumor microenvironment concerning HDAC2 or HDAC7 expression in all tested tumor types." (PMID 39063083, 2024). "Overall, our data indicate that HDAC2 is overexpressed in many EWS tumor samples and HDAC inhibition is effective in targeting EWS cells." (PMID 39518006, 2024). "SCA, a powerful and specific HDAC2 inhibitor, has been demonstrated to effectively suppresses tumour progression both in vitro and in vivo." (PMID 38804602, 2024). "IHC staining of tumor tissue sections showed that subcutaneous tumors transfected with LV-sh-HDAC2 had decreased ATG3 expression, increased p62 expression, and significantly reduced proliferation." (PMID 39147759, 2024). "HDAC2 inhibitors combined with PD-1 antibodies have been shown to significantly delay tumor growth and improve survival in syngeneic MC38 mouse models." (PMID 38654302, 2024). "Behavioral stress increased the β-AR signaling, which promoted tumor angiogenesis by inducing the epigenetic regulator histone deacetylase-2 (HDAC2)." (PMID 38397396, 2024). "HDAC2 expression in the tumor tissues of cisplatin-resistant patients was increased compared to those sensitive to cisplatin." (PMID 38087046, 2024). "Overexpression of HDACs, such as HDAC1 and HDAC2, results in the deacetylation of histones at tumor suppressor gene promoters, further repressing their expression and fostering tumor growth." (PMID 39596558, 2024). "To further validate these findings in vivo, we established a xenograft tumor model and observed that the reduced tumor volume in the HDAC2 knockdown group was rescued upon overexpression of LAPTM4B." (PMID 39147759, 2024). "For example, the expression of HDAC2/3/7/10 and SIRT2/3/6/7 associates with tumor size in BRCA, the level of HDAC4/5/8/10/11 and SIRT1/5/7 associates with tumor size in KIRC, and the upregulation of HDAC2/4/6/7 and SIRT1/2/6 associates with tumor size in LUAD." (PMID 39063083, 2024). "Using an orthotopic model of CRC, we found that HDAC2 KO tumours were more sensitive to treatment with regorafenib or 5‐FU than wild‐type tumours." (PMID 38804602, 2024). "This confirms high immune infiltration and stroma presence in the tumor tissues associated with HDAC7-high and HDAC2-low expression." (PMID 39063083, 2024).
tumor (continued). "In other words, HDAC7-high and HDAC2-low patients have significantly higher tumor immune and stromal infiltration levels in many tumors." (PMID 39063083, 2024). "IHC staining of tumor tissues demonstrated that CAY10683 effectively suppressed HDAC2 expression, attenuating both HDAC2-induced autophagy and proliferation, as well as LAPTM4B expression." (PMID 39147759, 2024). "In the subcutaneous tumor experiment in nude mice, overexpression of HDAC2 promoted AML growth in vivo." (PMID 38822351, 2024). "An aberrant expression of HDAC2 was clearly visible in the tumor tissues, especially in the proximal colon." (PMID 37046620, 2023). "This perspective aims to ignite enthusiasm for exploring the application of ideal HDAC2 inhibitors with solid anti-tumor efficacy in combination with immunotherapy for HCC." (PMID 37716965, 2023). "This suppression of HDAC2 not only regulates the level of T lymphocyte subsets and inhibits tumor immune suppression but also enhances the effectiveness of PD-1 inhibitors." (PMID 37716965, 2023). "Research has demonstrated that HDAC2 plays a pivotal role in regulating the cell cycle and apoptosis in both normal and tumor cells." (PMID 37495623, 2023). "In contrast, the study revealed a significant correlation between overexpression of HDAC2 and increased lymphatic spread of the tumor, as well as aggressive tumor behavior." (PMID 37175524, 2023). "In summary, the recruitment of cofactor TRPS1 by the activated PR differently altered the acetylation level of RANKL via establishing the PR/TRPS1/HDAC2 complex in EC and BC, thus affecting tumor behaviors." (PMID 37344459, 2023). "Therapeutically, the inhibition of histone deacetylase 2 restores the normal acetylation level of PD-L1, blocking its nuclear translocation and thereby attenuating tumor angiogenesis." (PMID 36977660, 2023). "Compared to PD-L1WT group, PD-L1K263R is more resistant towards HDAC2 inhibition, with increased capacity of promoting tumor growth and blood vessels formation." (PMID 36977660, 2023). "Subsequently, RT-qPCR results showed that relative to Pem alone, Pem + ITF2357 markedly decreased the expression levels of HDAC2 and Rad51 in tumor tissues of mice while increasing that of miR-130a-3p were increased." (PMID 36793108, 2023). "Class I HDAC knockout of individual HDACs, such as HDAC1 and HDAC2, inhibited invasiveness and blocked local tumor growth in xenografted mice." (PMID 36968022, 2023). "Tissue microarrays likewise demonstrated high levels of HDAC2 protein in tumor tissues compared with those of paracancerous tissues and distal tissues." (PMID 37171044, 2023). "CUDC-907, a dual inhibitor of HDACs and the phosphatidyl inositol-3 kinase (PI3K)/AKT pathway, suppressed tumor growth by decreasing the expression levels of HDAC2, p-AKT, and p-ERK1/2." (PMID 36968022, 2023). "HDAC2 inhibitors Trichostatin A in combination with anti-PD-1 antibodies enhance tumor growth inhibition and improve survival in MC38 homozygous use models." (PMID 37554324, 2023). "In summary, this study examined the expression of HDAC-2 in 118 deceased sporadic BC patients and its correlation with clinicopathological characteristics of the tumor and the prognosis of the patient." (PMID 36294811, 2022). "In the early stages of T-cell development, HDAC1 and HDAC2 were also considered to act as tumor suppression, as either deletion of the first one or monoallelic loss of the second one in the absence of HDAC1 resulted in spontaneous lymphomagenesis." (PMID 35887172, 2022). "By catalyzing the removal of acetyl groups on the NH2-terminal lysine histone residues, HDAC-2 is involved in transcriptional repression and tumor-suppressor gene-silencing." (PMID 36294811, 2022).
tumor (continued). "In all cases, the expression of either inactive HDAC1 or HDAC2 was sufficient to sensitize cells for tumor drug treatment." (PMID 35994477, 2022). "In vitro and in vivo experiments demonstrated that silencing TRPS1 inhibited tumor growth, whereas HDAC2 overexpression promoted it." (PMID 35359455, 2022). "For example, the histone deacetylase gene HDAC1 was upregulated across all sample groups except for LB fHER2− tumours, and the histone deacetylase gene HDAC2 was only upregulated in CLs." (PMID 36220861, 2022). "Another study proved that a natural HDACIs can reduce HDAC-2 levels in BC cell lines and lead to apoptosis and inhibition of tumor cell proliferation." (PMID 36294811, 2022). "Mechanistically, they showed that HDAC2 protected undifferentiated PDAC cells from the tumor suppressive functions of TGFβ signaling." (PMID 35158814, 2022). "The authors presented a dosage-dependent model of HDAC1 and HDAC2 in tumor suppression, with the HDAC1 being the key histone deacetylase in thymocytes." (PMID 35887172, 2022). "Collectively, the results from this study establish HDAC2 as an important epigenetic regulator of PDAC tumor biology and metastasis." (PMID 35158814, 2022). "HDAC2 is highly expressed in human tumor tissues, and overexpression of HDAC2 induces tumor cell proliferation, blocks apoptosis and promotes tumorigenesis." (PMID 35941558, 2022). "The HDAC2-maintained program disrupted the tumor-suppressive arm of the TGF-β pathway, explaining impaired metastasis formation of HDAC2-deficient PDAC." (PMID 35965507, 2022). "In particular, cases with mild HDAC-2 nuclear expression seemed to have the smaller tumor size in comparison to the rest expression levels." (PMID 34638249, 2021). "On the other hand, the detection results for protein and mRNA confirmed that the expression of PD-L1 in HDAC2-KO tumor tissues was significantly reduced than WT group." (PMID 34365463, 2021). "CRISPR/Cas9 class I HDAC knockout of individual HDACs such as HDAC1 and HDAC2 inhibited invasiveness, and blocked local tumor growth in xenograft mice." (PMID 34654445, 2021). "HDAC10 function as a tumor suppressor in stem-like lung adenocarcinoma and has been shown to interact with HDAC2." (PMID 34880761, 2021). "HDAC2 and PD-L1 have been reported to have both pro-tumorigenesis and immunomodulatory effects, which contributes to the formation of tumor-immunosuppressive microenvironment." (PMID 34365463, 2021). "RNA interference-mediated silencing of HDAC2 in HPV18-positive HeLa cells increased expression of the p21CIP1/WAFf1 tumor suppressor and stimulated apoptosis." (PMID 34361112, 2021). "Related to HDAC class I signaling, FK506 Binding Protein 3 (FKBP3) regulated HDAC2 expression contributing to the drug resistance in tumor cells." (PMID 34540896, 2021). "Compared to tumor from WT group, the HDAC2-KO group had a higher percentage of CD45+ lymphocytes, CD3+, and CD8+ T cells, but not CD4+ population or CD4+FOXP3+ Treg cells." (PMID 34365463, 2021). "In support of the result, HDAC2 knockout reduced the PD-L1 expression, promoted tumor lymphocyte infiltration, inhibited tumor growth, and metastasis in mouse models." (PMID 34365463, 2021). "We noticed that HDAC2 expression was correlated with tumor diameter, degree of differentiation and TNM stage." (PMID 33926524, 2021). "HDAC-1 was associated with increased tumor size, HDAC-6 with mitotic index, and HDAC-2 with epithelioid cell morphology, presence of ILS, and gain of chromosome 8q, all parameters of adverse prognosis." (PMID 34638249, 2021). "HCT116 cells stably expressing control or HDAC2 shRNA were injected into the splenic capsule of nude mice to form xenograft tumours." (PMID 33325150, 2021). "Overall, these results indicate that the HDAC2-KO changed the T-lymphocyte proportions of tumors and reduced the immunosuppression of tumor-bearing mice." (PMID 34365463, 2021).
tumor (continued). "Interferon gamma (IFNγ) represents a major driving force behind PD-L1 expression in tumor microenvironment, and histone deacetylase 2 (HDAC2) is required for IFN signaling." (PMID 34365463, 2021). "It was depicted that Ec109 cells with reduced HDAC2 formed smaller tumor volume and lighter tumor weight." (PMID 33926524, 2021). "A significant difference in the size of tumor was observed between the four levels of HDAC-2 nuclear expression according to IRS (Kwallis ANOVA p = 0.01)." (PMID 34638249, 2021). "MiR-500a-5p was confirmed to be a tumour suppressor that was significantly downregulated in CRC, inhibited CRC tumour growth and metastasis by regulating HDAC2 and was negatively regulated by YY1." (PMID 33865381, 2021). "HDAC-1 nuclear expression was associated with increased tumor size (p = 0.03), HDAC-6 with higher mitotic index (p = 0.03), and nuclear HDAC-2 with epithelioid cell morphology (p = 0.03) and presence of tumor-infiltrating lymphocytes (p = 0.04)." (PMID 34638249, 2021). "HE staining and RT-qPCR were performed with mice tumor sections and exhibited that HDAC2 inhibition repressed tumor growth." (PMID 33926524, 2021). "HDAC2 protein expression in the primary tumour tissue samples from 121 patients was detected by immunohistochemistry (IHC)." (PMID 33325150, 2021). "Higher HDAC2 expression correlated with lymphatic tumour spread (p = 0.046) and lower tumour differentiation grade (p = 0.002)." (PMID 34439236, 2021). "The shared molecular targets of HDAC inhibitors identified via this drug screening were HDAC1 and HDAC2, suggesting that one or both play roles in the growth of core-like tumor cells." (PMID 32938908, 2020). "BC tumor tissues and their corresponding normal tissues were analyzed for miR-489-3p and HDAC2 by in situ hybridization and IHC staining." (PMID 32774482, 2020). "HDAC1 and HDAC2, which are class I HDACs, exhibit a wide range of expression in tumours and strong enzymatic activity for many histone substrates." (PMID 31993801, 2020). "FK228, a specific HDAC1 and HDAC2 inhibitor, was shown to have anti‐tumour effects though inducing G1/S transition arrest in GBM in vitro and in vivo." (PMID 31993801, 2020). "Consistently, it has been revealed that inhibition of HDAC2 upregulated the miR-183 and exhibits tumor suppressive functions." (PMID 32723328, 2020). "Ectopic expression of miR-145 inhibits cell growth and HDAC2 expression; inhibits tumor growth in vivo." (PMID 32906681, 2020). "According to the results, there was an inverse relationship between the expression levels of miR-489-3p and its downstream target histone deacetylase 2 (HDAC2) in BC tumor tissues." (PMID 32774482, 2020). "Following this, the expression of miR-489-3p and HDAC2 in BC tumor tissues at different clinical stages (1, 2, 3 and 4) was examined." (PMID 32774482, 2020). "USP4 interacted with tricho-rhino-phalangeal syndrome type I to form a complex which led to HDAC2 deubiquitination, then promoted tumor growth both in vitro and in vivo." (PMID 32669974, 2020). "The importance of HDAC1 and HDAC2 in tumor cell survival provides a good rational for treating CML cells with imatinib in combination with pan-HDACis." (PMID 32430012, 2020). "It has been reported that USP5 promotes tumor proliferation and tumorigenesis through the deubiquitination of histone deacetylase 2 (HDAC2) and β-catenin." (PMID 32477134, 2020). "Mechanistically, HDAC2 can bind to the promoter of CD1d and HDAC2 knockdown in tumor cells results in a significant increase of CD1d surface expression, thus enhancing CD1d-mediated immune recognition and activation of NKT cells." (PMID 32162275, 2020). "Our studies demonstrate that miR-500a-5p functions as a tumour suppressor in CRC by targeting the p300/YY1/HDAC2 axis, which contributes to the development of and provides new potential candidates for CRC therapy." (PMID 30737378, 2019).